S100A8 (S100 calcium binding protein A8)
Diseases named in the same sentence as S100A8 in open-access papers (continued):
Sharing a sentence is not in itself a finding about the gene and the disease.
osteosarcoma (5 papers, 2020 to 2025). A usually aggressive malignant bone-forming mesenchymal neoplasm, predominantly affecting adolescents and young adults. "CD48, TIMD-4, B7-H6, CD134, B7-H5, CD47, and S100A8/A9 were significantly elevated in osteosarcoma patients, each linked to increased osteosarcoma risk." (PMID 40963634, 2025). "With the exception of B7-H2, all measured immune checkpoint proteins—CD48, TIMD-4, B7-H6, CD134, B7-H5, CD47, and S100A8/A9—were significantly elevated in osteosarcoma patients compared to healthy controls (p < 0.05)." (PMID 40963634, 2025). "Additionally, S100A8 levels were elevated in the plasma of metastatic osteosarcoma patients, while its transcriptional levels in tumor tissues were decreased." (PMID 40963634, 2025). "Interestingly, we also observe an increase of S100A8 and S100A9 expression in the pre-metastatic lungs of osteosarcoma-bearing mice." (PMID 33233625, 2020).
peripheral artery disease (5 papers, 2015 to 2025). "Based on the results from selecting hub genes among 15 potential candidate genes, four hub genes were selected that were significantly upregulated in both CD and peripheral arterial disease: S100A8, S100A9, S100A12, and CXCR2." (PMID 40422241, 2025). "The pathways associated with neutrophil activation, chemotaxis, and migration were significantly correlated with the high expression of S100A8, S100A9, S100A12, and CXCR2 in CD and peripheral arterial disease." (PMID 40422241, 2025). "Platelet S100A8/A9 levels are also increased in patients with SLE and peripheral artery disease and are thought to promote thrombosis and cardiovascular disease." (PMID 37733441, 2023). "In human studies, the two calprotectin subunits S100A8 and S100A9 were detected in atherosclerotic plaques and elevated in serum of patients suffering from peripheral artery disease." (PMID 26663990, 2015).
peritonitis (5 papers, 2017 to 2023). Inflammation of the peritoneum (tissue that lines the abdominal wall and covers most of the organs in the abdomen). "This work characterizes the role of S100A8/A9 on host resolution of inflammation in an experimental model of disseminated C. albicans peritonitis." (PMID 33717058, 2021). "High amounts of S100A8/A9 were released in the peritoneal lavage fluid and plasma of peritonitis affected mice, and this lead to liver and lung damage, and high cytokine production, because in S100A9 KO mice, the organ damage was reduced and the cytokine production was diminished." (PMID 29180999, 2017). "In a collagenase-induced OA model, S100A8 and S100A9 expression remained elevated long after inflammatory cytokine levels had subsided, while in a BCP crystal-induced peritonitis model, both peritoneal and serum concentrations of S100A8 and S100A9 were increased." (PMID 28173838, 2017).
schizophrenia (5 papers, 2012 to 2024). A major psychotic disorder characterized by abnormalities in the perception or expression of reality. "Previous studies have reported increased S100A8/9/12 gene expression in peripheral blood cells, prefrontal cortex, and hippocampus of individuals with schizophrenia." (PMID 35898501, 2022). "In a mouse model study, S100A8 expression increases significantly after chronic treatment with the antipsychotic drug olanzapine, which is used primarily to treat schizophrenia and bipolar disorder patients." (PMID 23282246, 2012). "This study identified key molecular changes in schizophrenia, notably the upregulation of S100A8, S100A9 and BCL2A1 and thedownregulation of CBLB, highlighting the involvement of neuro-inflammatory pathways, apoptosis regulation and immune modulation in thedisease." (PMID 40162448, 2024). "The upregulation of S100A8 and S100A9 aligns with the role of calprotectin, aheterodimeric protein complex involved in neuroinflammation, in schizophrenia." (PMID 40162448, 2024). "Our study confirms the upregulation of S100A8 and S100A9 in schizophrenia, which has been well-documented in previous research." (PMID 40162448, 2024). "Additionally, the potential of S100A8, S100A9 and EGF as biomarkersfor disease severity and treatment response opens new possibilities for personalized therapeutic approaches in managing schizophrenia." (PMID 40162448, 2024). "Inflammation related genes including S100A8, S100A9 and CHI3L1 are elevated in the hippocampus in schizophrenia and perivascular macrophages (CD163+) have been identified in the lumen of blood vessels and surrounding the endothelial cells in at least one schizophrenia hippocampus." (PMID 30214039, 2020).
septic shock (5 papers, 2019 to 2024). Shock caused by infection; frequently caused by gram negative bacteria, although some cases have been caused by other bacteria, viruses, fungi, and protozoa; characterized by fever, chills, tachycardia, tachypnea, and hypotension. "We measured plasma levels of two DAMPs, S100A8/S100A9 and S100A12 during the first 24 h of admission of septic shock patients." (PMID 31666644, 2019). "In a small study in 17 septic shock patients, S100A8/A9 levels decreased in surviving patients during recovery while non-survivors were characterized by high S100A8/A9 serum levels." (PMID 32425933, 2020).
Sjögren’s syndrome (5 papers, 2011 to 2025). "In Sjogren’s syndrome affecting exocrine glands, especially salivary and lacrimal glands, S100A8/A9 has been identified as a biomarker." (PMID 35529863, 2022).
Streptococcus pneumoniae infection (5 papers, 2012 to 2021). "It has been reported that S100A8 and 9 are induced by both SP- and NTHi-infection, and they are major players in the host response against pneumococcal infection by increasing lung recruitment of neutrophils and macrophages." (PMID 33784296, 2021). "Antibodies against S100A8 also reduce cell migration to the dorsal air pouch in response to inflammation induced by LPS or by monosodium urate crystals and to the lungs in response to Streptococcus pneumoniae infection." (PMID 31437241, 2019). "Studies of opioid abuse have shown that morphine treatment resulted in diminished secretion of the antimicrobial proteins, S100-A9 and S100-A8/A9, in lung tissue and samples of bronchoalveolar lavage fluid during the early stages of Streptococcus pneumoniae infection." (PMID 22860055, 2012).
systemic juvenile idiopathic arthritis (5 papers, 2016 to 2024). "Some studies showed that systemic juvenile idiopathic arthritis (systemic JIA) is associated with high concentrations of S100A8/A9." (PMID 27537874, 2016). "A similar correlation between serum S100A8/A9 levels and skin rash presence was found in patients with systemic-onset JIA." (PMID 38672106, 2024).
thrombosis (5 papers, 2024 to 2025). "Strikingly, the blood of COVID‐19 patients with thrombosis contains high levels of circulating NETs, S100A8 and S100A9, along with an abundance of immature neutrophils in the bloodstream." (PMID 38319150, 2024). "The plasma S100A8/A9 level is drastically enhanced in patients with VTE and correlates with thrombosis, which may be a novel diagnostic marker and therapeutic target of VTE." (PMID 40422770, 2025). "Simultaneously, we constructed a rat model of thrombosis induced by inferior vena cava stenosis and detected levels of S100A8, VCAM-1, and ICAM-1 in the blood of DVT rats using ELISA." (PMID 38858401, 2024).
adenoma (4 papers, 2012 to 2024). A neoplasm arising from the epithelium. "In the advanced adenoma group, differences between the healthy mucosa and adenomatous tissue were found in S100A6 (p = 0.002), S100A8 (p = 0.002), S100A9 (p = 0.021) and S100A11 (p = 0.029)." (PMID 33466593, 2021).
allergic asthma (4 papers, 2024 to 2026). A asthma with a basis in a pathological type I hypersensitivity reaction. "This study aimed to determine the effects of S100A8/A9 on macrophage polarization and glycolysis associated with allergic asthma." (PMID 38646478, 2024). "In an allergic asthma model, calprotectin S100A8/A9 drives M1 polarization via the TLR4/MyD88/NF κB axis and markedly augments glycolysis, as indicated by raised lactate and glycolytic enzymes." (PMID 41602451, 2026). "In murine models of allergic asthma, deletion or inhibition of S100A8 or S100A9 has been shown to reduce airway inflammation, eosinophilic infiltration, and structural remodeling." (PMID 40723384, 2025). "OVA-induced allergic asthma increased all levels, whereas S100A8 and S100A9 knockdown decreased the levels in OVA-sensitized and challenged mice (p < 0.01)." (PMID 38646478, 2024). "Further investigation is necessary to differentiate the effects of S100A8/A9 on the proportion of macrophage subtypes in allergic asthma." (PMID 38646478, 2024). "We established a mouse model of allergic asthma using OVA to observe the protective effects of S100A8 and S100A 9 knockdown in the lungs post-OVA-challenged." (PMID 38646478, 2024). "Study in allergic asthma mice and MHS alveolar macrophages further demonstrate that the damage-associated molecular pattern S100A8/A9 enhances glycolysis and lactate production via TLR4/MyD88/NF-κB signaling, concomitant with increased ACLY phosphorylation and upregulation of M1 signature factors." (PMID 41602451, 2026). "The TLR4/MyD88/TRIF/NF-κB signaling pathway and ACLY activity were inhibited in OVA-induced MH-S cells with knockdown of S100A8 or S100A9 and allergic asthma mice, suggesting that knockdown of S100A8 or S100A9 inhibits glycolysis by suppressing the TLR4/MyD88/TRIF/NF-κB signaling pathway." (PMID 38646478, 2024). "Overexpression of S100A9 can exacerbate lung injury and inflammation in patients with allergic asthma, whereas inhibition of S100A8 and S100A9 can stabilize macrophage polarization and inhibit glycolysis to improve allergic asthma." (PMID 40880642, 2025). "To verify the role of S100A8 and S100A9 in allergic asthma mice, we assessed respiratory function, observed pathological damage to lung tissue, and measured the levels of inflammatory cells and cytokines in BALF." (PMID 38646478, 2024). "Our study highlights that S100A8 and S100A9 play critical roles in the pathogenesis of allergic asthma by promoting macrophage perturbation and glycolysis through the TLR4/MyD88/NF-κB signaling pathway." (PMID 38646478, 2024). "The in vivo results of our study demonstrated that the knockdown of S100A8 or S100A9 inhibited M1 and M2 macrophage polarization and improved respiratory function and lung injury in mice with allergic asthma." (PMID 38646478, 2024). "Our study highlighted the potential of inhibiting S100A8 and S100A9 to ameliorate allergic asthma by stabilizing macrophage polarization and inhibiting glycolysis." (PMID 38646478, 2024). "S100A8 and S100A9 play critical roles in allergic asthma pathogenesis by promoting macrophage perturbation and glycolysis through the TLR4/MyD88/NF-κB signaling pathway." (PMID 38646478, 2024). "To better understand the roles of S100A8 and S100A9 in the pathogenesis of allergic asthma, we used ovalbumin (OVA)-induced MH-S cells, and OVA-sensitized and challenged mouse models (wild-type male BALB/c mice)." (PMID 38646478, 2024). "In addition, 3-BP, an inhibitor of HK-II, antagonized the effects of S100A9 overexpression, suggesting that HK-II is a key gene involved in the S100A8 and S100A9 regulation of glycolysis in mice with allergic asthma, which warrants further investigation." (PMID 38646478, 2024). "S100A8 and S100A9 may be involved in the regulation of macrophage polarization, glycolytic metabolism, and pyroptosis in allergic asthma." (PMID 38646478, 2024).
allergic asthma (continued). "Inhibition of S100A8 and S100A9 may be a potential therapeutic strategy for allergic asthma." (PMID 38646478, 2024).
ANCA-associated vasculitis (4 papers, 2018 to 2025). "Research indicates that in the management of patients with severe ANCA-associated vasculitis, azathioprine exerts an immunosuppressive effect during induction of remission, thereby lowering S100A8 and subsequently reducing the risk of recurrence for patients." (PMID 40475761, 2025). "In patients with active antineutrophil cytoplasm antibody (ANCA)–associated vasculitis (AAV), renal biopsies demonstrate glomerular infiltration of S100A8/S100A9-positive immune." (PMID 36017003, 2022).
angina pectoris (4 papers, 2013 to 2023). The symptom of paroxysmal pain consequent to MYOCARDIAL ISCHEMIA usually of distinctive character, location and radiation. "Accordingly, this clinical evidence supports that S100A8/A9 is a feasible biomarker to distinguish patients with ACS from those with stable angina and that elevated circulating S100A8/A9 is clinically relevant to long-term adverse prognosis." (PMID 33282877, 2020). "Additionally, a clinical study showed that compared with patients with stable angina pectoris or individuals with normal coronary artery morphology assessed by coronary angiography, circulating S100A8/A9 levels were highly elevated in patients with ACS." (PMID 33282877, 2020). "As the sustained inflammatory response associated with myocardial necrosis following an MI is absent in unstable angina, these patient groups should be assessed separately with regard to the prognostic value of S100A8/A9 in secondary prevention." (PMID 24453429, 2013).
Anxiety (4 papers, 2016 to 2023). Intense feelings of nervousness, tension, or panic often arise in response to interpersonal stresses. "T-lymphocyte expression of S100a8 and S100a9 showed a similar positive correlation with anxiety-like behavior, but also positively correlated with the corner zone ratio of the social interaction test." (PMID 31139062, 2019). "Collectively, these results suggest that GA can bind S100A8 to improve cognition through the immune system in all groups of mice without anxiety, and this effect is partially eliminated by mutating the GA binding site in S100A8." (PMID 36906583, 2023). "Stress-induced upregulation of S100A8 and S100A9 has also been reported previously in mouse hippocampus, though it is unclear if S100A8/A9 expression in the CNS is beneficial or detrimental to stress and anxiety." (PMID 34758843, 2021).
Arrhythmia (4 papers, 2023 to 2025). Any cardiac rhythm other than the normal sinus rhythm. "infection increases mortality by causing severe cardiac electrical dysfunction and arrhythmia, and that S100A8/A9 released by neutrophils is essential for providing protection against the P. a." (PMID 37624851, 2023). "The three-condition framework for arrhythmia occurrence (i.e., substrate, trigger, and modulating factors) is a well-recognized concept in electrophysiology, and S100A8/A9 seems to influence all of them." (PMID 40948795, 2025). "However, direct experimental evidence linking these anti-inflammatory actions of S100A8/A9 to concrete arrhythmia outcomes or electrophysiological endpoints is presently lacking." (PMID 40948795, 2025).
arteriosclerosis (4 papers, 2017 to 2024). A vascular disorder characterized by thickening and hardening of the walls of the arteries. "GeneChip analysis revealed increased six key genes during the process of arteriosclerosis including Apol11b, Camp, Chil3, S100a8, S100a9, and Spta1." (PMID 36982506, 2023). "Considering the results of the most sensitive vascular endothelium in culture, Camp, Chil3, and S100a8 may be considered the most effective markers of ongoing arteriosclerosis." (PMID 36982506, 2023).
Cachexia (4 papers, 2022 to 2024). Severe weight loss, wasting of muscle, loss of appetite, and general debility related to a chronic disease. "Atrophic effects of S100A8, S100A9, and S100A8/A9 indicated them as potential pathogenic factors of PC-induced cachexia." (PMID 37280516, 2023). "Tumors of PC patients with cachexia had markedly elevated expression of S100A8 (P = 0.003) and S100A9 (P < 0.001)." (PMID 37280516, 2023). "In conclusion, in vitro atrophic effects of S100A8, S100A9, and S100A8/A9 suggest their potential as pathogenic factors of PC-induced cachexia." (PMID 37280516, 2023). "Taken together, changes in IL-6, TNF-α or other pro-inflammatory factors reported previously might be the consequences of the complex tumor-incited immunological responses mediating cachexia, whereas our results support that S100A8, S100A9 and S100A8/A9 are potential drivers of PC-induced cachexia." (PMID 37280516, 2023). "PC patients with cachexia had significantly higher serum levels of S100A8, S100A9 and S100A8/A9." (PMID 37280516, 2023). "Although it is well known that systemic inflammation drives cancer cachexia and S100A8, S100A9, and S100A8/A9 have potent proinflammatory functions, the link between these factors and PC-induced cachexia has not been discovered previously." (PMID 37280516, 2023). "In addition, serum levels of either S100A8, S100A9, or S100A8/A9 did not correlate with those of IL-6 or TNF-α in PC patients with cachexia (n = 80)." (PMID 37280516, 2023).
chronic pancreatitis (4 papers, 2013 to 2025). A chronic inflammatory process causing damage and fibrosis of the pancreatic parenchyma. "In line with our results, previous research has demonstrated significant overexpression (> 10-fold) of S100A8 in pancreatic adenocarcinoma, whereas S100A8 and S100A9 were rarely expressed in normal pancreatic tissue and tissue of chronic pancreatitis." (PMID 37280516, 2023).
contact dermatitis (4 papers, 2012 to 2025). An inflammatory skin condition caused by direct contact between the skin and either an irritating substance or an allergen. "The S100A8/S100A9 tetramer modulates the immune response in skin granuloma and irritant contact dermatitis models by regulating the basal migration of monocytes through specific interactions with CD69." (PMID 40270593, 2025). "Previous analysis of the skin response to P. ovis infestation demonstrated an increase in the expression of S100A9 and the putative conserved roles of S100A8 and S100A9 in contact dermatitis and sheep scab have been discussed previously." (PMID 22880105, 2012). "It is demonstrated that extracellular S100A8/S100A9 tetramers significantly dampen monocyte dynamics as adhesion, migration, and traction force generation in vitro and immigration of monocytes in a cutaneous granuloma model and inflammatory activity in a model of irritant contact dermatitis in vivo." (PMID 36310133, 2022).
coronary atherosclerosis (4 papers, 2009 to 2025). Atherosclerosis of the coronary vasculature. "Despite significant advances in understanding the role of S100A8/A9 in coronary atherosclerosis, HF, and cardiac arrhythmogenesis, several critical knowledge gaps warrant further investigation, especially in terms of mechanistic understandings and clinical translation from experimental studies." (PMID 40948795, 2025).